POU4F3 (POU class 4 homeobox 3)
Diseases named in the same sentence as POU4F3 in open-access papers (continued):
Sharing a sentence is not in itself a finding about the gene and the disease.
autosomal dominant nonsyndromic hearing loss (10 papers, 2014 to 2023). Autosomal dominant form of nonsyndromic deafness. "The pathogenic variant, POU class 4 transcription factor 3 (POU4F3), is reported to cause autosomal dominant nonsyndromic hearing loss (ADNSHL)." (PMID 34250087, 2021). "DFNA15, caused by mutations of the transcription factor POU4F3, is one of the most common types of autosomal dominant non-syndromic deafness." (PMID 32970669, 2020). "In this study, we describe a pathogenic missense mutation in POU4F3 in a four-generation Chinese family (6126) with midfrequency, progressive, and postlingual autosomal dominant nonsyndromic hearing loss (ADNSHL)." (PMID 29850532, 2018). "Mutations in the POU class 4 transcription factor 3 (POU4F3) are known to cause autosomal dominant nonsyndromic hearing loss linked to the loci of DFNA15." (PMID 29850532, 2018). "Several mutations of POU4F3 have been reported to cause autosomal dominant nonsyndromic hearing loss in recent years." (PMID 27999687, 2016). "The most remarkable finding was a gradient of gene expression changes in four genes (Pou4f3, Slc17a8, Tmc1, and Crym) whose mutations cause autosomal dominant deafness." (PMID 24676347, 2014). "Especially for genes whose mutations cause autosomal dominant non syndromic hearing loss (Pou4f3, Slc17a8, Tmc1, and Crym) as well as genes important for cochlear function (Emilin-2 and Tectb), gradual expression changes may help to explain the various pathological conditions." (PMID 24676347, 2014). "POU4F3, a member of the POU family of transcription factors, commonly causes autosomal dominant deafness." (PMID 37537203, 2023). "DFNA15, caused by mutations of the transcription factor POU4F3, is one of the most common forms of autosomal dominant non-syndromic deafness." (PMID 32970669, 2020). "Mutation of POU domain class 4 transcription factor 3 (POU4F3) is considered the pathogenic cause of autosomal dominant nonsyndromic hearing loss (ADNSHL), designated as autosomal dominant nonsyndromic deafness." (PMID 32684921, 2020). "In this study, 10 SNPs located in the POU4F3 and GRHL2 genes, which are regarded as the genes of autosomal dominant deafness, taking into account noise exposure, were analyzed in a Chinese sample set." (PMID 27271650, 2016).
cervical cancer (6 papers, 2015 to 2024). A primary or metastatic malignant neoplasm involving the cervix. "We propose a scenario for the combination of HPV assay and POU4F3 methylation analysis for cervical cancer screening." (PMID 26300990, 2015). "The combined use of broad-spectrum HPV assay and POU4F3 methylation analysis as a new generation of molecular cervical cancer screening warrants further population-based study." (PMID 26300990, 2015). "Furthermore, an assay designed to evaluate the POU4F3 gene methylation in liquid-based cytology samples of HPV-positive women appeared to be a noteworthy method for cervical cancer detection and is under clinical trial evaluation." (PMID 37511475, 2023). "The methylation levels of the POU Class 4 Homeobox 3 (POU4F3) gene are increased in cervical cancer, which may indicate a tumor-suppressor role of this gene despite the fact that its function in carcinogenesis is unknown." (PMID 37047452, 2023). "DNA methylation analysis of SOX1 and POU4F3 in cervical scrapings consistently detects cervical cancer and the majority of CIN3 lesions, and has the capacity to broaden its use on cervical scrapings through the detection of a substantial subset of complex hyperplasia." (PMID 26057869, 2015). "POU4F3 hypermethylation in cervical cancer and glioma suggests its suppressor role in cancer." (PMID 26300990, 2015).
sensorineural hearing loss (3 papers, 2016 to 2021). "In this study, we identified four novel variants in the POU4F3 gene, three missense variants, and one frameshift variant, which led to sensorineural hearing loss in four different Chinese families." (PMID 32684921, 2020). "Therefore, impairment of hair cells in the cochlea caused by pathogenic variants of POU4F3 has been considered as one of the major causes of sensorineural hearing loss." (PMID 32684921, 2020).
endometrial cancer (2 papers, 2025). Primary or metastatic malignant neoplasm involving the endometrium (mucous membrane that lines the endometrial cavity). "Utilizing cervical scrapings as a potential genetic material, coupled with the use of DNA hypermethylation in specific genes, including CDO1, CELF4, BHLHE22, POU4F3, MAGI2, CADM1, MAL, miR124-2, ZSCAN12, and GYPC, has been investigated for endometrial cancer detection." (PMID 41008854, 2025).
Merkel cell carcinoma (2 papers, 2022 to 2025). "Here, we show that MCPyV+ Merkel cell carcinoma is defined by neuroendocrine-lineage core regulatory (CR) transcription factors (TFs) (ATOH1, INSM1, ISL1, LHX3, POU4F3, and SOX2) that were essential for tumor survival and that co-bound chromatin with the viral small T antigen at super enhancers." (PMID 41392987, 2025).
adenomyosis (1 paper, 2022). The growth of endometrial tissue inside the muscular wall of the uterine corpus. "In the present study, abnormal expression of spexin (SPX), cannabinoid receptor 2 (CNR2) and POU class 4 homeobox (POU4F3) may have been involved in sensory perception of pain in the myometrium of women with and without adenomyosis, relevant to dysmenorrhoea." (PMID 35773139, 2022).
cervical disease (1 paper, 2015). "All cases of significant cervical disease (CIN3+ /CIS or worse lesions) and complex hyperplasia of the endometrium were detected by methylation markers SOX1and POU4F3, with a sensitivity of 100% (95% CI,59–100) and specificity of 67% (95% CI,52–80) and 52% (95% CI,37–67), respectively." (PMID 26057869, 2015).
hepatocellular carcinoma (1 paper, 2022). A malignant tumor that arises from hepatocytes. "We found that the expression of POU4F3 in hepatocellular carcinoma tissue was higher than that in adjacent liver tissues (P < 0.05), whereas there was no statistical difference in other types of cancers." (PMID 35069902, 2022).
lung carcinoma (1 paper, 2022). "However, the relationship between POU domain class IV transcription factor III (POU4F3) and lung cancer remains unknown." (PMID 35069902, 2022). "However, the relationship between POU4F3 and lung cancer has not yet been elucidated." (PMID 35069902, 2022).
lymph node metastasis (1 paper, 2022). "However, the differences in age, gender, tumor size, tumor location, differentiation grade (P > 0.05), or lymph node metastasis between the POU4F3-high and the POU4F3-low groups were not statistically significant (P > 0.05)." (PMID 35069902, 2022).
Marshall syndrome (1 paper, 2021). "The corresponding phenotypic disorders of the mutated POU4F3, COL11A1, OCA2 are autosomal dominant deafness type 15, Marshall syndrome (or Stickler syndrome) and eye pigment variant I, respectively." (PMID 33345266, 2021).
nonsyndromic hearing loss (1 paper, 2014). "Of the 23 probands, six had mutations in DFNA genes [WFS1 (n = 2), COCH, ACTG1, TMC1, and POU4F3] known to cause autosomal dominant nonsyndromic hearing loss." (PMID 25388789, 2014).
progressive hearing loss (1 paper, 2020). "Correspondingly, mutations of POU4F3 also caused human late onset, progressive hearing loss (DFNA15) in multiple families." (PMID 32390314, 2020).
tumor (4 papers, 2022 to 2025). "POU4F3, a transcription factor involved in neuronal differentiation, is often hypomethylated in EC, leading to its overexpression and promoting tumor cell survival and resistance to apoptosis." (PMID 40528483, 2025). "This study indicated that POU4F3 may work as a tumor suppressor in LUAD via regulating the PERK/eIF2α/ATF4/CHOP pathway." (PMID 35069902, 2022). "For the first time, our study demonstrated that POU4F3 is a novel tumor suppressor gene in LUAD." (PMID 35069902, 2022). "Likewise, tumors with stable POU4F3 knockdown illustrated that POU4F3 inhibition potentiated tumor growth (P < 0.001)." (PMID 35069902, 2022).
cancer (3 papers, 2015 to 2022). A tumor composed of atypical neoplastic, often pleomorphic cells that invade other tissues. "By other two methylomic methods, we further discovered Zinc finger protein 582 (ZNF582), AJAP1, HS3ST2, and POU4F3 are highly methylated in cancer and precancerous lesions." (PMID 26057869, 2015). "The function of POU4F3 in cancer biology remains largely unknown." (PMID 26300990, 2015). "The function of SOX1 and POU4F3 in cancer biology remain largely unknown." (PMID 26057869, 2015). "However, determining POU4F3 methylation in HPV-negative women to assess POU4F3 as independent from HPV as a marker for cervical neoplasia/CIN/CIN3/cancer may also be a consideration." (PMID 26300990, 2015).
infection (3 papers, 2018 to 2021). The state of being infected such as from the introduction of a foreign agent such as serum, vaccine, antigenic substance or organism. "(C) Images of MEFs reprogrammed with Six1, Atoh1, Pou4f3, and Gfi1 (SAPG) fixed at 14 days post infection (dpi)." (PMID 32602462, 2020). "In our experimental set-up we confirmed the expression of MYOSIN VIIA protein and MYOSIN VIIA, POU4F3 and ESPIN mRNAs after 12 days of infection." (PMID 29979748, 2018).
POU4F3 also shares sentences with these, for which no sentence is quoted: Hearing impairment (2 papers); adenocarcinoma of the colon (1); breast carcinoma (1); colorectal adenoma (1); genetic disease (1); glioma (1); lung adenocarcinoma (1); noise induced hearing loss (1); Onset (1); retinal tumors (1); Stickler syndrome (1).